CD4 (CD4 molecule)
Diseases named in the same sentence as CD4 in open-access papers (continued):
Sharing a sentence is not in itself a finding about the gene and the disease.
tumor (continued). "It is known that low human leukocyte antigen (HLA)-DR expression might compromise CD4+ T-cell-mediated anti-tumor immunity." (PMID 38790277, 2024). "In addition, we found that the anti-tumor effects of zebularine depend on the co-existence of CD4+ and CD8+ T lymphocytes." (PMID 38755254, 2024). "While critical to effective anti-tumor responses, key aspects of CD4+ T-cell exhaustion remain unclear." (PMID 39689157, 2024). "The equilibrium among different subsets of CD4+ T cells, their cytokine production, and interactions with other immune cells in the tumor microenvironment collectively determine whether the immune response favors tumor growth or inhibits it." (PMID 38426090, 2024). "The crucial marker of immune response in tumor is the proportion of immune cells including cytotoxic T cells (CD3+CD8+) and helper T cells (CD3+CD4+), which could be evaluated by counting immune cells extracted from tumor." (PMID 38774946, 2024). "The presence of such tumor-reactive B cells and their intrinsic ability to process and present antigens may support the maintenance of a functional memory CD4+ T cell population." (PMID 38306431, 2024). "Interestingly, a relationship between HLA-DR+ tumor cell expression and the degree of CD4+ T helper cell tumor infiltration was observed." (PMID 38822345, 2024). "Adaptive immunity mediated by CD8+ and CD4+ T cells is the leading force for killing tumor cells." (PMID 39735340, 2024). "Only trending differences in the CD4 compartment were observed in BA-treated tumours." (PMID 38622286, 2024). "Importantly, JHU083 treatment reduces immunosuppressive cell populations in murine models, including monocyte and granulocyte-derived suppressive cells, regulatory T cells, and pro-tumor CD4 + Th17 cells." (PMID 38459595, 2024). "Our findings reveal that EphB4 knockdown in cancer cells leads to an increase in the development of distant metastases, characterized by a pro-metastatic cancer cell phenotype, systemic immunosuppression, and enhanced infiltration of CD4+ T cells and Tregs into the tumor." (PMID 39091728, 2024). "At the same time, the results showed that 30 tumours were related to B cells, 30 tumours were related to CD8+T cells, 31 tumours were related to CD4+T cells, 24 tumours were related to macrophages, 33 tumours were related to neutrophils and 37 tumours were related to DCs." (PMID 38146591, 2024). "Additionally, CD8+Tregs were observed to be more distant from tumor cells, while being closer to CD4+T cells and CD8+T cells in IM and TC." (PMID 39093404, 2024). "It is worth noting that the interaction between HLA‐II molecules (such as HLA‐DRA, HLA‐DRB1, HLA‐DRB5, HLA‐DQB1, HLA‐DPB1, HLA‐DPA1, HLA‐DMB and HLA‐DMA) and the receptor CD4 was exclusively detected in the cell communication between malignant cells from single‐primary tumours and Tregs." (PMID 39601163, 2024). "For instance, if the CD4 + T-cell infiltrate is indeed IL-4/IL-13 secreting, this may have functional consequences on the non-tumor cells of the TME." (PMID 38285120, 2024). "Additionally, it was observed that the depletion of CD4+ T cells in mice while targeting CD47 led to a slight elevation in the tumor volume compared to targeting CD47 alone." (PMID 38398223, 2024). "Indeed, immunosurveillance of hyperploid tumor cells was shown to involve both CD4+ and CD8+ T lymphocytes as well as type I and type II IFN." (PMID 39544936, 2024). "The tumor‐infiltrating CD4+ T cells were comparable between all treatment groups." (PMID 39054639, 2024). "Furthermore, mature MDSCs lead to effective CD4+ Th1-dominant anti-tumor immunity and result in a significantly increased survival rate in mice." (PMID 38791188, 2024). "The MC-38 model provided a unique opportunity to rigorously compare tumor-unrelated and tumor-specific help in neoantigen vaccination, as we and others recently identified CD8+ and CD4+ T cell neo-epitopes on this highly mutated, MHC class II-negative tumor cell line." (PMID 39040850, 2024).
tumor (continued). "However, memory CD4 + T cells can exert anti-tumour immune effects through multiple mechanisms, such as directly regulating the expression of granzyme and perforin and indirectly regulating the production of CD8 + memory T cells." (PMID 38825615, 2024). "In addition, tumors of CS-like FS have significantly higher proportions of activated CD4 memory T cells, and high levels of tumor infiltrating lymphocytes are well documented to predict good response to PD-1 blockade." (PMID 38978078, 2024). "We hypothesize that extended ICI treatment achieves a tumor microenvironment in which CD4/CD8 TIL levels are high and FOXP3 levels are low, contributing to the downregulation of VEGF signaling." (PMID 38013668, 2024). "In the present study, however, we were unable to detect any significant associations between PD-1+ T cells and survival, with the exceptions being CD8+PD-1+/CD4+PD-1+ in predicting tumor response and OS, and CD8+/CD4+ in predicting OS in the univariate analysis of all patients." (PMID 38404585, 2024). "Observing a correlation between CD4+ T cells in blood and tumor, we asked if specific CD4+ T phenotypes could predict T cell infiltration into tumor." (PMID 38653982, 2024). "Analysis of the correlation between R3HDM1 expression and immune infiltration levels in TCGA tumor profiles using seven different algorithms revealed a significant positive association of R3HDM1 expression with B cells, CD4+T cells, CD8+T cells, and Treg cells in nearly all cancer types." (PMID 39376739, 2024). "In addition, CD40-signaling-induced CCL5 elicits tumor infiltration by CD4+ T cells and enables immunosuppression of cancer growth." (PMID 39114657, 2024). "Conversely, in advanced stages of cancer, there is a notable increase in CD4+ TILs, with a shift in dominance to Treg and Th17 cells, which may facilitate tumor growth." (PMID 39507526, 2024). "Given the increased tumor development in the CD4-depleted mice and the later time point of harvest, we hypothesize that earlier time points of evaluation may have noted histological differences between treatment groups." (PMID 39339897, 2024). "Additionally, loss of ID3 leads to an increase in the CD4 Th9 phenotype, exhibiting potent antitumour immunity, and adoptive TIL therapy using tumour specific CD4 Th9 cells demonstrates potent antitumour activity." (PMID 39676870, 2024). "Of note, endogenous CD4+CD25+FoxP3+ T cells found within the tumor expressed both NRP1 and Plexin-A1 as well as TGFβR1-2, indicating that this subset of T cells might be modulated differently from CD8+ T cells." (PMID 38609390, 2024). "Interestingly, the density of both CTL and CD4+ cell subsets was significantly higher in TLS areas compared to the entire tumor area." (PMID 39376565, 2024). "Additionally, Th1-polarized CD4+ cells release cytokines such as interferon-gamma and tumor necrosis factor-alpha, which improve antigen presentation by dendritic cells and enhance tumor cell recognition." (PMID 39769460, 2024). "However, at D17, the elimination phase is likely to be predominant, with effective tumor recognition and greater production of cytokines by CD4+ T lymphocytes." (PMID 38690280, 2024). "Furthermore, the blockade of CD4 has demonstrated an enhanced immunogenicity immune response against the tumor." (PMID 38397971, 2024). "Then, we revealed that PCSK9i could elevate MHC-II+ and antigen-presenting CD103+ DC proportions in spleen cells, sensitize tumor cells to be killed by T cells, and indirectly activate both CD4+ and CD8+ T cells in vitro." (PMID 38600469, 2024). "Cellular neighbourhoods analysis indicated that both macrophages (p = 0.003) and effector CD4+ T cells (p = 0.01) in mixed tumour neighbourhoods, as well as CD8+ T cells (p = 0.03) in HLADR+ tumour neighbourhoods were associated with favorable clinical response." (PMID 38439077, 2024). "KCC2 positively correlated with the levels of tumor-infiltrating macrophages and CD4+ T cells." (PMID 39061990, 2024).
tumor (continued). "Our study is the first to report that the downregulated expression of CD3+ and CD4+ T cells may be correlated with pCR and tumor regression induced by administration of a PD‐1 antibody in pMMR/MSS CRC patients." (PMID 38888366, 2024). "However, the bulk ofthe antitumor effect of CD4+ Th cells is the Th-mediated activationof CTLs to recognize and destroy tumor cells or activate other immune cells, inparticular the B cell component of the immune response." (PMID 39555171, 2024). "Therefore, CD45RA on CD39+ resting CD4 regulatory T cells, by degrading the pro-inflammatory factor ATP and inhibiting the anti-tumor effects of other immune cells, creates a more permissive immune environment for tumor cells." (PMID 38566827, 2024). "It is of interest that particular CD4 T cell helper subsets might be critical components of such immune cell clusters, and may determine tumor evolution and responsiveness to immune checkpoint inhibitors." (PMID 40604303, 2024). "Similarly, the MAPK1 signaling pathway plays a role in regulating dendritic cells, CD4+ T cells, and tumor antigen-specific CD8+ T cells." (PMID 39867914, 2024). "Tregs, belonging to a specialized CD4+ T cell subpopulation, accumulate in tumors and are overactivated in diverse carcinomas to maintain immune tolerance and homeostasis and to hinder effective anti-tumor immunity." (PMID 39227959, 2024). "For instance, M-CSF can enhance the proliferation of tumor-associated dendritic cells while reducing their activation and antigen-presenting capacity, leading to functional impairments and an inability to induce the proliferation of tumor-specific CD4+ and CD8+ T cells." (PMID 38646440, 2024). "Other tumor infiltrating lymphocytes of interest were the CD4+ helper T cells." (PMID 38954689, 2024). "Interestingly, the proximity score of CD4+Tregs to tumor cells, CD4+T cells, and CD8+T cells were similar to CD4+Tcons." (PMID 39093404, 2024). "Hence, the variables of tumor-infiltrating CD4+ T high/CD8+ T high/%Tregs low and tumor-infiltrating %M1 high/M2 low are appropriate for assessing the immune microenvironment of PDAC." (PMID 38730579, 2024). "We also observed effector cells (e.g., NK cells and CD8+ Tcyto) significantly correlated with EC favorable prognosis were plentiful in the normal sample, whereases the level of exhausted (CD8+ Tex and CD4+ Tex) and Treg cells (CD4+ Treg) increased in tumor samples." (PMID 39112478, 2024). "Moreover, ICOS expression was considerably higher in tumor-infiltrating T cells than circulating T cells, particularly among conventional CD4+ T cells (p<0.001)." (PMID 38384469, 2024). "In addition, STC1 is significantly associated with patient prognosis and influences tumor immunity by mediating six types of immune cells (CD8+T cells, CD4+T cells, neutrophils, macrophages, monocytes, and B cells) in the tumor microenvironment." (PMID 39201771, 2024). "Furthermore, both in colorectal cancer (CRC) and non-small cell lung cancer (NSCLC), Duhen and colleagues demonstrated tumour-reactive CD4+ Th or follicular T helper (Tfh) TILs co-express PD1 and ICOS." (PMID 38440738, 2024). "The “hot” tumor exhibited significantly higher infiltrations of various activated immune cells, including CD4 memory activated T cells, resting NK cells, M1 macrophages, and CD8 T cells, which demonstrated that TNBC patients with “hot” tumors had an immuno-active TIME." (PMID 39007147, 2024). "In addition, the expression of PD-1 was increased on CD4+ T cells of virus-infected birds at 21 dpi95, which prevented T cells from killing tumour cells or infected target cells in the setting of persistent infection and cancer." (PMID 38879650, 2024). "In addition, CD4+ effector T cells cooperate with activated iNOS expressing tumor-killer monocytes and macrophages to coordinate leading distal inflammatory cell death to eliminate MHC deletion and non-responsive cancer cells." (PMID 38279145, 2024).
tumor (continued). "Recent studies have shown that the presence of tumor-residing stem cell–like T cells is predictive of response, suggesting the potential of stem cell–like CD4 T cells as a pan-cancer predictive biomarker for treatment response." (PMID 39190534, 2024). "Moreover, the Eosinophils in the tumor microenvironment can cooperate with CD4 T cells to enhance the treatment response to immune checkpoint inhibitors." (PMID 39867887, 2024). "The accumulation of tumor-infiltrating CD4+ and CD8+ T cells reflected the differences in growth." (PMID 39178856, 2024). "Indeed, deletion of NFAT5 in a CD4 promoter-driven Cre-Lox recombination system improves tumour control by tumour-specific T cells in a mouse model of melanoma." (PMID 39399500, 2024). "In turn, CD4+ T cells accelerate tumor growth by releasing cytokines which in turn affect TAMs." (PMID 38957393, 2024). "Also, immunofluorescence (IF) and flow cytometry analyses revealed that PRMT3 inhibition led to a robust increase in the abundance of tumor-infiltrating CD4+ and CD8+ T cells, including IFNγ + CD8+ and GZMB+ CD8+ T cells." (PMID 39256398, 2024). "In vitro studies showed that agonistic engagement of SLAMF7 on tumor-specific CD4+ T-cells enhanced their cytolytic activity, which, if expressed by CD4+ T-cells in these tumors, may explain the relationship with favorable prognosis." (PMID 38476238, 2024). "Our findings revealed that anti-tumor immune cells comprised activated CD4 T cells, effector memory CD4 T cells, and type 17 T helper cells, while intermediate immunocytes included activated B cells, eosinophils, immature B cells, mast cells, and memory B cells." (PMID 39199281, 2024). "The TME might influence CD4+ T cells to produce cytokines with pro-tumorigenic functions, promoting tumor survival." (PMID 38292868, 2024). "Among these, CD4+ T cells, a type of inflammatory cell, are crucial in supporting and sustaining antitumor immune responses, which are predominantly mediated by the release of cytokines into the tumor microenvironment." (PMID 39079960, 2024). "Second, immune-desert tumor P25 exhibited CD4+T helper cell and B-cell neighborhoods." (PMID 39053947, 2024). "By contrast, anti-PD-1 mAb bound a large fraction of CD8+ and CD4+ T cells at the tumor site." (PMID 38417020, 2024). "Indeed, from single cell RNA sequencing and flow cytometry data, we demonstrated that cancer cells with high expression of Bcl6 inhibit tumor immune cell infiltration, and suppress tumor-infiltrating CD4+T cells and CD8+T cells activity." (PMID 38956432, 2024). "Notably, elevated ENO1 expression in the tumor and aging groups significantly increased CD4-positive, α-β regulatory T cell differentiation within Type 2 T helper cells, enhancing PD-L1 expression and the PD-1 checkpoint pathway activity." (PMID 39457014, 2024). "High PD-L1+ lymphocyte infiltration in tumour stroma was more common in tumours with higher CD4+ T cell infiltration in islets and stroma, Foxp3+CD4+ T cell infiltration in islets and lover M1 macrophage infiltration in the stroma (p = 0.034, p = 0.034, p = 0.005 and p = 0.034 respectively)." (PMID 39409156, 2024). "This might be due to the differences in methodology because the peripheral CD4+ T cells were defined with surface molecules at the protein level while the tumor-derived CD4+ T cells’ surface molecules were analyzed at the RNA level." (PMID 38343544, 2024). "In addition to their role in the tumor-draining lymph nodes, tumor-specific CD4+ T cells residing in the TME can contribute to tumor resistance, for example, by recruiting and providing local help to57 CD8+ T cells." (PMID 39040850, 2024). "The results of tumor microenvironment and immune cell infiltration analysis showed higher scores of immune, stromal and higher infiltration abundance of immune cells such as CD4 + T cells, CD8 + T cells and B cells in C2 subgroup." (PMID 38910160, 2024).
tumor (continued). "Hence, in this investigation, we examined the expression and location of CD4 cells in the FL tumor tissue using immunohistochemistry (IHC)." (PMID 39248131, 2024). "Besides maintaining homeostasis, F. prausnitzii was correlated with the immunostimulatory effects of ICI, increasing blood ICOS+CD4+ T cells and sCD25 serum levels as well as reprogramming of the tumor microenvironment." (PMID 38395948, 2024). "However, we also found that a portion of these mice were able to eliminate C-225 tumor, and these data suggest that other immune cells such as CD4 T cells can also mediate tumor eradication." (PMID 39055715, 2024). "Furthermore, CD8+ and CD4+ T cell densities in tumours were found to be significantly related to the response status." (PMID 38399453, 2024). "Importantly, the proportion of tumor killer CD8+ (TC or CTL cells) T cells was elevated to 56.94% and CD4+ T cells’ proportion has increased to 10.39% through radiosensitization in distant tumor." (PMID 38774946, 2024). "Additionally, they aggregate and activate immune cells such as CD4 andCD8 T cells, thus promoting tumor cell death (CT26 colorectal carcinoma and B16 melanoma in mouse)." (PMID 38887519, 2024). "How tumor expression of ING4 regulates the CD4 CTL fate in the TME is unclear." (PMID 38968186, 2024). "Tregs can dampen T cell effector function, whereas CD4 helper T cells play a critical role in the development of anti-tumor immunity by assisting in the development of cytotoxic CD8 T cells, secreting anti-tumor cytokines such as IFNγ and TNFα, and stimulating B cell production." (PMID 39104861, 2024). "Through multifaceted analyses including protein profiling, cellular subpopulation distribution, and receptor-ligand interactions, we identified key features of tumor remodeling of the peripheral immune system, mainly in the form of enhanced inflammation and changes in CD4+T cell function." (PMID 38735538, 2024). "However, the importance of CD4+ T cells in anti‐tumor immunity and their role in the response to PD‐1/PD‐L1 blockade has been increasingly recognized." (PMID 39248327, 2024). "In addition, lymphocytes are crucial in cancer immune surveillance by promoting tumor cell apoptosis and infiltrated lymphocytes (CD4+/CD8+ T-lymphocytes), which are among the most important members of host immunity." (PMID 39668902, 2024). "Additionally, STAT3 signaling in CD4+ T cells promotes regulatory T cell (Treg) accumulation in tumors while inhibiting CD8+ effector T (TEFF)tumor infiltration and antitumor immunity." (PMID 39618825, 2024). "In vivo SSO administration significantly attenuated mouse tumor growth with an increased proportion of immune cells, including CD4+ T, CD8+ T, and dendritic cells; it also decreased the proportion of immune suppressive cells, such as myeloid-derived suppressor and regulatory T cells." (PMID 39273384, 2024). "This module therefore identifies central-memory CD4 T cells to be enriched outside of the tumor." (PMID 39548591, 2024). "Immunophenotyping revealed an increase in intra-tumoral activated CD8+ T cells and conventional CD4+ T cells, along with a decrease in Tregs, indicating a shift from an immunosuppressive to a responsive tumor microenvironment and triggering a robust adaptive immune response." (PMID 39594765, 2024). "Together, these data demonstrated that vaccination with constructs containing CD4 helper antigens, most prominently with tumor-unrelated universal helper antigens (uniHELP), resulted in phenotypic changes in vaccine-induced CD8+ T cells that have been associated with improved effector functions." (PMID 39040850, 2024). "However, they can also exert a pro-tumor function by secreting IL-10, which inhibits CD4+ and CD8+ T cells." (PMID 38913547, 2024). "It was later demonstrated that the involvement of OX-40R during tumor initiation in vivo may enhance the function, expansion and survival of tumor-specific CD4+ T cells." (PMID 39329710, 2024).